SORT1 (sortilin 1)
Diseases named in the same sentence as SORT1 in open-access papers (continued):
Sharing a sentence is not in itself a finding about the gene and the disease.
tumor (continued). "Moreover, similar to CD320, the promoter methylation levels of SORT1 and PSMD14 were considerably lower in tumor tissues than in normal tissues, and there was also a negative correlation between gene expression and promoter methylation levels." (PMID 36959615, 2023). "The predominant cell surface localization of SORT1, as opposed to the expected ER-Golgi compartment, suggests a significant role in tumor cell interaction with the microenvironment, potentially affecting tumor growth and metastasis." (PMID 39033780, 2024). "A receiver operating characteristic (ROC) curve analysis of SORT1 methylation at cg16988986 showed an area under the curve (AUC) of 0.8 (95% confidence interval [CI]: 0.71–0.89), suggesting its potential utility in distinguishing tumor tissues from non-tumor tissues." (PMID 39209807, 2024). "Thus, by highlighting the significant relationship between immune cell infiltration and Sort1 expression, the results suggest not only that Sort1 is involved in the HCC tumor microenvironment but also that this process could be important for allowing tumor cells to evade the immune system." (PMID 35847356, 2022). "The SORT1+ cell proportion was notably higher in HCC cells than in normal and adjacent non-tumor cells." (PMID 39209807, 2024). "The interactions where non-tumor cells influenced tumor cells included NAMPT → INSR, MIF → CD74 and CXCR4, GRN → SORT1, and CD99 → CD99." (PMID 39095793, 2024). "However, despite the presence of significantly expressed ligand–receptor pairs in tumor cells, CAF1, and CAF2 cells (e.g., GRN/SORT1, PLA2G2A/a5b1 complex), there is a lack of spatial proximity between CAF1 and CAF2 cells." (PMID 38229179, 2024).
cardiovascular disease (15 papers, 2020 to 2024). "Plasma LDL-C levels are a significant risk factor for cardiovascular disease, and the SORT1 gene at the 1p13 locus has been associated with changes in LDL-C levels and cardiovascular risk." (PMID 38913092, 2024). "Some of these SORT1-associated functions lead to an increased risk of cardiovascular diseases." (PMID 36975855, 2023). "Indeed, INF-γ was identified as an important mediator in controlling sortilin-1 (Sort-1) levels, which is a receptor of VPS10p family associated with cardiovascular disease, including the reduction in Sort-1 by INF-γ regulated by JAK/STAT pathway." (PMID 37112866, 2023). "A cluster of three genes CELSR2, PSRC1, and SORT1 has been associated with cardiovascular diseases." (PMID 36975855, 2023). "Sortilin, encoded by SORT1, serving as a key receptor for lipids, cytokines, and enzymes and participating in pathological cargo loading to and trafficking of extracellular vesicles, is also known for its functional role in metabolic disorders and cardiovascular disease." (PMID 38166912, 2024). "GWAS approaches suggest that the SORT1 gene carries the strongest association with low-density lipoprotein cholesterol (LDL-C) of all loci, suggesting a role of sortilin in metabolic and cardiovascular diseases." (PMID 38339069, 2024). "A library of in-house small molecules and currently used therapeutics for cardiovascular diseases were screened using AutoDock Vina to assess the targetability of human SORT1." (PMID 38255751, 2024). "A vast number of GWAS have identified SNPs in SORT1 strongly associated with LDL cholesterol and risk of cardiovascular disease." (PMID 36397124, 2022). "In essence, this study not only advances our understanding of SORT1’s role in cardiovascular diseases but also introduces promising avenues for developing therapeutics that could have far-reaching implications across diverse medical disciplines." (PMID 38255751, 2024). "Several SNPs associated with cardiovascular disease are proximal to both CELSR2 and PSRC1, however the region containing these SNPs was found to interact with SORT1 located 120 kb away, supporting a previous study that SORT1 is the target gene of this region." (PMID 35377406, 2022). "In particular, the Sortilin 1 gene (SORT1) has been extensively studied as a target gene of the associated variants and shown to regulate circulating low-density lipoprotein levels influencing risk of cardiovascular diseases." (PMID 32620998, 2020). "The identification of SORT1 as a driver of microcalcification processes in cardio-valvular and cardiovascular diseases, irrespective of lipid metabolism and cholesterol levels, underscores its pivotal role in pathophysiological mechanisms beyond traditional risk factors." (PMID 38255751, 2024).
infection (5 papers, 2011 to 2025). The state of being infected such as from the introduction of a foreign agent such as serum, vaccine, antigenic substance or organism. "In vivo, Sort1-deficient mice exhibited substantially increased cellular infiltration of neutrophils and higher bacterial burden after infection with Mycobacterium tuberculosis in the lungs, suggesting that Sort1-dependent delivery of Asm into phagosomes is crucial for restricting bacterial growth." (PMID 33153072, 2020). "In vivo, Sort1−/− mice showed a substantial increase in cellular infiltration of neutrophils in their lungs and higher bacterial burden after infection with M. tuberculosis." (PMID 27389464, 2016). "After 3 and 7 days of infection, a significant increase in the survival of M. tuberculosis was observed in Sort1−/− macrophages compared to Sort1+/+, as determined by CFU analysis." (PMID 27389464, 2016). "BMM from Sort1−/− mice showed a significant increase in the M. tuberculosis-EGFP fluorescence intensity signal at the single cell level compared with Sort1+/+ macrophages after 7 days of infection." (PMID 27389464, 2016). "More importantly, we observed a significant increase in the size of infiltrated areas in the lungs of Sort1−/− mice after different infection times." (PMID 27389464, 2016). "Downregulation of Sort1 by miR-H1 thus allows cell infection and evasion of host immune responses." (PMID 29559974, 2018). "Additionally, we observed more rapid dissemination into spleens after 28 and 56 days of infection in Sort1−/− mice." (PMID 27389464, 2016). "However, the total fluorescence intensity of BCG-DsRed per cell increased in BMM from Sort1−/− mice after 2 h of infection compared to BMM from Sort1+/+." (PMID 27389464, 2016). "In bone-related diseases, SORT1 promotes cell death by mediating apoptotic signals dependent on neurotrophic factors, such as proNGF, and may exacerbate bone tissue damage and resorption following infection." (PMID 41050653, 2025). "Using a low dose infection, mimicking conditions associated with natural aerosol transmission (CFU between 100–200), we identified a modest but significant difference in bacterial load among Sort1−/− and Sort1+/+ mice after 14 and 56 days post-aerosol challenge." (PMID 27389464, 2016). "After 24 h of infection, the total CFU of mycobacteria was 190.77% higher in Sort1−/− macrophages than in Sort1+/+ macrophages." (PMID 27389464, 2016). "A reduction of ASMase association with M. tuberculosis-containing phagosomes occurred in Sort1−/− compared to Sort1+/+ BMM after 3 and 7 days of infection." (PMID 27389464, 2016). "However, a quantitative analysis showed that the association of ASMase was significantly higher in mycobacteria-containing phagosomes from Sort1+/+ compared to Sort1−/− BMM at 1, 6 and 24 h of infection." (PMID 27389464, 2016). "We observed a significant decrease in the number of mycobacterial phagosomes positive for LAMP-2 in bone marrow macrophages (BMM) from Sort1−/− mice compared to mycobacterial phagosomes in Sort1+/+ BMM (Mean = 450.5 ± 47.29 vs. 303.4 ± 31.83, respectively) after 2 h of infection." (PMID 27389464, 2016).
metabolic disease (4 papers, 2022 to 2025). A congenital disorder (due to inherited enzyme abnormality) or acquired (due to failure of a metabolically important organ) disorder resulting from an abnormal metabolic process. "Proteomic analysis illustrated that the expression of certain proteins including AGRP, LEP and SORT1 associated with metabolic diseases decreased following THD treatment." (PMID 40242450, 2025).
neurodegenerative disease (3 papers, 2023 to 2025). A disorder of the central nervous system characterized by gradual and progressive loss of neural tissue and neurologic function. "Importantly, all of these synaptic regulators (Nos1, Lrp8, Argef2, Sema5b) and other significantly altered splice variants (e.g., Adipor2, Mapk14, Smarca4, Sort1, Mapt) have been linked to AD and other neurodegenerative diseases." (PMID 37819053, 2023). "In neurodegenerative diseases, where aberrant protein aggregation and inflammatory responses are prevalent, SORT1’s influence on monocytes and tissue remodelling may contribute to disease progression." (PMID 38255751, 2024).
adenocarcinoma (2 papers, 2017 to 2024). A common cancer characterized by the presence of malignant glandular cells. "In fact, a highly intriguing finding from our study is that while SORT1 is downregulated in both adenocarcinoma and SCCs, low SORT1 expression is associated with poor outcome in adenocarcinomas, while it marginally appears to be favourable for patients with squamous cancers of the lung." (PMID 38893272, 2024). "Using primary NSCLC surgical specimens, we verified the downregulation of SORT1 in both adenocarcinomas and SCC." (PMID 38893272, 2024). "Interestingly, in all the datasets analysed, a low SORT1 expression was associated with poor overall and disease-free survival in adenocarcinomas, while in SCC, either non-significant or borderline trends with favourable outcome were derived between SORT1 expression and survival." (PMID 38893272, 2024).
immune diseases (2 papers, 2023 to 2024). "Its interaction with SORT1 can influence its levels and activity and is hence seen as a promising therapeutic target for immune diseases." (PMID 39627184, 2024).
bacterial infection (1 paper, 2018). "Interestingly, the expression of Sort1 is induced in bacterial infection suggesting its role in activation of innate immunity against diverse pathogens." (PMID 29559974, 2018).
benign tumor (1 paper, 2022). "Within the samples tested here using TMAs, SORT1 expression was observed in about 60% of the benign tumor samples as well as in the germ cell and non-epithelial tumors." (PMID 35454785, 2022).
heart diseases (1 paper, 2015). "Lastly, noncoding SORT1 variation has recently been associated with high cholesterol levels and heart diseases." (PMID 26297037, 2015).
SORT1 also shares sentences with these, for which no sentence is quoted: Hypertension (5 papers); Alzheimer disease (4); Hypercholesterolemia (4); Hepatic steatosis (3); Parkinson disease (2); psoriasis (2); rheumatoid arthritis (2); Abdominal obesity (1); age-related macular degeneration (1); alopecia areata (1); aortic aneurysm (1); aortic stenosis (1); Cerebral ischemia (1); cervical cancer (1); chronic kidney failure (1); Clear Cell Carcinoma (1); colonic adenocarcinoma (1); coronary artery calcification (1); coronary stenosis (1); dementia (1); encephalomyelitis (1); gram-positive bacterial infections (1); Graves disease (1); gynecological tumors (1); Hepatic fibrosis (1); Huntington disease (1); Hyperglycemia (1); hyperuricemia (1); hypolipoproteinemia (1); idiopathic intracranial hypertension (1).
A further 11 diseases each share a sentence with SORT1 in 1 paper.